ETS2 (ETS proto-oncogene 2, transcription factor)
Diseases named in the same sentence as ETS2 in open-access papers (continued):
Sharing a sentence is not in itself a finding about the gene and the disease.
heart failure (4 papers, 2024 to 2025). Inability of the heart to pump blood at an adequate rate to meet tissue metabolic requirements. "Indeed, ETS2 is a transcription factor involved in development and apoptosis; therefore, they suggested that the modulation of ETS2 expression may be a new therapeutic approach for the treatment of heart failure." (PMID 40823532, 2025). "In the present study, we elucidated that high Ets2 expression in the heart is regulated by Ets2-SE and SMC3, providing potential insights for precision therapy of heart failure patients." (PMID 39085358, 2024).
intestinal tumors (4 papers, 2009 to 2024). "Notably, in the same study, different dosages of ETS2 alleles in mice corresponded closely to the incidence of intestinal tumors in the APCmin background." (PMID 38255007, 2024). "Initially categorized as a proto-oncogene linked to acute megakaryoblastic leukemia when involved in somatic balanced translocations, a pivotal study utilizing mouse models of DS revealed that overexpression of ETS2 in APCmin mice prevented the development of intestinal tumors." (PMID 38255007, 2024).
osteosarcoma (4 papers, 2022 to 2025). A usually aggressive malignant bone-forming mesenchymal neoplasm, predominantly affecting adolescents and young adults. "Subsequently, we performed silence and overexpression functional experiments of IBSP and ETS2 in the osteosarcoma cell lines." (PMID 38755647, 2024). "Similarly, ETS2 was also highly expressed in osteosarcoma cell lines." (PMID 38755647, 2024). "In brief, we identified and verified the key role of ETS2/IBSP, a new signaling axis, in LN metastasis in osteosarcoma, which could provide new targets and direction to block metastasis." (PMID 38755647, 2024). "Moreover, we discovered and validated the role of a new signaling axis, ETS2/IBSP, in LN metastasis of osteosarcoma." (PMID 38755647, 2024).
Sepsis (4 papers, 2017 to 2023). Sepsis is defined as life-threatening organ dysfunction caused by a dysregulated host response to infection. "Moreover, Ets2 knockout mice were more susceptible than wild-type mice to CLP-induced sepsis." (PMID 31785145, 2019). "In this study, we identified 8 senescence-related genes (IGFBP7, GMFG, IL10, IL18, ETS2, HGF, CD55, and MMP9) and developed a diagnostic model for the prediction of sepsis occurrence." (PMID 38259686, 2023). "A comprehensive analysis was conducted to investigate the impact of senescence-related genes on sepsis, and 8 hub genes (IGFBP7, GMFG, IL10, IL18, ETS2, HGF, CD55, MMP9) associated with senescence were identified." (PMID 38259686, 2023). "Consistently, Ets2-deficient mice show exacerbated inflammatory cytokine production and are more susceptible to CLP-induced sepsis." (PMID 31785145, 2019). "We measured cytokine expression and production of IL-6, TNF-α and IFN-β in Ets2 knockdown or knockout macrophages and susceptibility to cecal ligation and puncture (CLP)-induced sepsis in Ets2-deficient mice." (PMID 31785145, 2019). "The enrichment analysis indicated that transcription factors (ETS2 and the IRF family) play roles in the regulation of multiple sepsis-associated modules." (PMID 29237456, 2017). "After demonstrating the negative regulation of Ets2 on proinflammatory cytokine production, we asked whether Ets2 plays a protective role in mouse endotoxemia or sepsis." (PMID 31785145, 2019). "Moreover, in severe sepsis model (cecum ligated for 1cm in CLP procedure), Ets2-deficient mice also showed increased IL-6 and TNF-α production in serum and poor survival." (PMID 31785145, 2019). "Whereas little is known about the impact of ETS2 on sepsis and further investigation is needed." (PMID 29237456, 2017). "Among them, transcription factors of particular interest are ETS proto-oncogene 2, transcription factor (ETS2) and the interferon regulatory transcription factor (IRF) family, as they function in the regulation of multiple sepsis-associated co-expression modules." (PMID 29237456, 2017). "Consensus cluster analysis we successfully classified sepsis patients into two distinct groups based on the expression of 8 hub genes (IGFBP7, GMFG, IL10, IL18, ETS2, HGF, CD55, and MMP9)." (PMID 38259686, 2023). "Gene ontology of these 23 common DEGs showed that apoptotic process (TRAF1, TNFRSF9, ADORA2A, ZBTB16), negative regulation of transcription (SAP30, TSC22D3, ETS2, ZBTB16), and inflammatory response (TNFRSF9, CCL3, ADORA2A) are the main biological processes affected by sepsis treatment." (PMID 30086151, 2018).
thyroid cancer (4 papers, 2014 to 2025). "Previous work has implicated Ets1/Ets2 and c-Myc collaboration in invasive breast cancer and in thyroid cancer in humans." (PMID 24968297, 2014). "Understanding the ETS2-ZMYND11 axis offers deeper insights into their collaborative role in thyroid cancer and suggests potential therapeutic targets for THCA management." (PMID 40938895, 2025). "ETS2, a gene involved in cellular response and senescence, is a key factor in thyroid cancer progression." (PMID 40938895, 2025). "The outcomes revealed a notable rise in the quantity of Cal-62 and TPC-1 apoptotic cells following ETS2 overexpression, indicating that ETS2 enhances apoptosis in thyroid cancer cells." (PMID 40938895, 2025). "To further validate the tumor-suppressive role of ETS2 in thyroid cancer, we established a mouse xenograft model using Cal-62 cells overexpressing ETS2 or a control vector." (PMID 40938895, 2025). "In our study, while we have made significant progress in understanding the roles of ETS2 and ZMYND11 in thyroid cancer, we must acknowledge that our research has certain limitations." (PMID 40938895, 2025).
COVID-19 (3 papers, 2021 to 2024). A disease caused by infection with severe acute respiratory syndrome coronavirus 2. "Consistently, the regulons including GATA2, SPI1, ETS2, FLI1, and ETV6 were activated in COVID-19 patients." (PMID 34349096, 2021). "Collectively, MkP- and GP-priming TFs, including ETS2, FLI1, SPI1, and GATA2 were activated in the HSC/MPP cells from COVID-19 patients, probably contributing to the increased output of myeloid progenitor cells and decreased output of lymphoid progenitors." (PMID 34349096, 2021). "In addition, we conducted score analysis to examine the transcriptional level of TF-downstream target genes, and identified substantial increase in scores of ETS2, FLI1, and SPI1 in COVID-19 patients compared with controls." (PMID 34349096, 2021). "Up-regulation of ETS2, FLI1, GATA2, and ETV6 in the HSC/MPPs of COVID-19 patients raised the speculation that the HSC/MPPs preferentially differentiated into MkP cells." (PMID 34349096, 2021). "Regarding the MkP-priming TFs, significant co-expression of ETS2-FLI1-GATA2-PBX1 and SPI1-LMO4 was observed in the HSC/MPPs from COVID-19 patients, with 75.8% and 61.4% of HSC/MPPs co-expressing ETS2 and FLI1 in the mild and severe cases, respectively, compared with 8.4% in HC." (PMID 34349096, 2021). "For instance, IL1B, NFKB1, NLRP3, PYCARD, and CASP1 are listed in the COVID-19 Disease Map, while there are molecules absent from it, including CCL3, 3L1, 4L2, CXCL1, 2, 3, 5, 16, TNFAIP6, C15orf48, TMEM176A/B, NFE2, PADI4, RAB20, ETS2, PHLDA2, FOLR3, and HP." (PMID 37719701, 2023).
Crohn disease (3 papers, 2023 to 2025). A gastrointestinal disorder characterized by chronic inflammation involving all layers of the intestinal wall, noncaseating granulomas affecting the intestinal wall and regional lymph nodes, and transmural fibrosis. "The rs2836882 variant has previously been implicated in autoimmune and inflammatory diseases such as Crohn’s disease and ulcerative colitis, where it enhances ETS2 transcription in monocytes." (PMID 41465135, 2025). "Overexpression of ETS2 induces inflammatory pathways, closely emulating the transcriptional profile observed in macrophages of inflammatory diseases such as Crohn’s disease." (PMID 41465135, 2025). "Interestingly, we also observed higher ETS2 expression in both Crohn’s disease (CD) and ulcerative colitis (UC), two major types of IBD, than in normal colon controls." (PMID 36609474, 2023).
esophageal squamous cell carcinoma (3 papers, 2016 to 2022). Esophageal squamous cell carcinoma (ESCC) is a type of esophageal carcinoma (EC) that can affect any part of the esophagus, but is usually located in the upper or middle third. "In the present study, we found that ETS2 was highly expressed in GC, which was consistent with the expression of ETS2 in esophageal squamous cell cancer." (PMID 34261460, 2021). "Increased expression of Ets2 is reported upregulated in esophageal squamous cell carcinoma tissue." (PMID 27556183, 2016).
glioma (3 papers, 2021 to 2024). A benign or malignant brain and spinal cord tumor that arises from glial cells (astrocytes, oligodendrocytes, ependymal cells). "Supporting the idea of a pro-tumoral effect associated with ID2 expression, and inversely anti-tumoral property linked to ETS2 expression in GB tumours, high ID2 and ETS2 gene expression levels were found to be associated respectively with poor and good prognosis in cohort of patients with gliomas." (PMID 39019900, 2024). "Supporting our findings, the analysis of these TGCA gene expression dataset revealed that ID2 should be considered as an unfavourable prognostic gene whereas ETS2 as a favourable prognostic gene for patients with glioma." (PMID 39019900, 2024). "Furthermore, ID2 and ETS2 gene expressions exhibited inverse prognostic values for patients with glioma." (PMID 39019900, 2024). "Furthermore, ID2 and ETS2 gene expressions exhibited inverse prognostic values in patients with glioma in cohorts from The Cancer Genome Atlas." (PMID 39019900, 2024). "Here, we report the identification in vitro of an ID2 (corepressor)-ETS2 (transcription factor) regulatory axis involved in the acquisition of a tumour-supportive phenotype by BV2 microglia once exposed to stimuli originating from C6 glioma cells." (PMID 39019900, 2024). "In glioma cell lines, we found a statistically significant decrease in ETS2 expression." (PMID 36142793, 2022). "On the contrary, bioinformatic analysis of transcriptomic data from glioma patients revealed a decrease in gene expression of ETS2 regardless of the degree of malignancy." (PMID 36142793, 2022). "Likewise, our result suggests that ETS2 could exert similar functions in microglia, which could be repressed by the induction of ID2 expression in those cells when they are recruited and converted into tumour-trophic cells by the glioma cancer cells." (PMID 39019900, 2024). "The analysis of regulon activity scores showed that, while ELK-1 and ETS2 showed high regulon activity in the non-tumor condition (magenta), ETV1 showed a high activity score on mainly grade 2 glioma (green)." (PMID 33671331, 2021).
hepatocellular carcinoma (3 papers, 2016 to 2023). A malignant tumor that arises from hepatocytes. "A high Ets2 protein level in early stage of hepatocellular carcinoma has also been found." (PMID 27556183, 2016). "In order to test whether Ets2 plays a role in the upregulation of CD13 expression by ROS in HCC, we firstly collected hepatocellular carcinoma data sets from the Cancer Genome Atlas (TCGA) data and analyzed the correlation between CD13 and Ets-2 gene expression." (PMID 34045966, 2021).
leukemia (3 papers, 2012 to 2020). A malignant (clonal) hematologic disorder, involving hematopoietic stem cells and characterized by the presence of primitive or atypical myeloid or lymphoid cells in the bone marrow and the blood. "As in Drosophila, both TEL1 and ETS1/ETS2 operate as Ras pathway transcriptional effectors and misregulated activity of either factor has been implicated in many human leukemias and solid tumors." (PMID 22615925, 2012).
renal cell carcinoma (3 papers, 2020 to 2021). "ETS2 is over-expressed in breast, prostate, and renal cell carcinomas, and its deletion inhibits the survival and metastasis of these cells." (PMID 34261460, 2021). "The down-regulation of ETS2 significantly reduces the level of p-AKT in renal cell carcinoma cells." (PMID 34261460, 2021).
STAR syndrome (3 papers, 2017 to 2025). "Interestingly, some morphologic features of STAR syndrome patients might be caused by abnormally high ETS2 levels, which, in Ets2 transgenic mice, cause a number of cranial and skeletal defects." (PMID 32762766, 2020). "Hence, the combination of enhanced ETS2 levels and ciliary defects resulting from compromised CDK10/CycM activity may explain most, if not all, of the clinical features of STAR syndrome." (PMID 28178678, 2017).
adenoma (2 papers, 2016 to 2025). A neoplasm arising from the epithelium. "Similar to our results, adenoma-specific stem cells were shown to originate from TIC-like populations expressing ETS2, SLC12A2, and LEFTY1." (PMID 41282138, 2025).
atherosclerosis (2 papers, 2023 to 2024). A disease characterized by the build-up of fatty material and calcium deposition in the arterial wall resulting in partial or complete occlusion of the arterial lumen. "ETS2 deficiency may lead to endothelial dysfunction and injury, which accelerates the progression of atherosclerosis and promotes cardiovascular disease." (PMID 38292407, 2024).
colorectal adenocarcinoma (2 papers, 2021 to 2024). The most common type of colorectal carcinoma. "ETS2 also has a role in carcinogenesis and is up-regulated in a number of cancers, notably including colorectal adenocarcinoma and hepatocellular carcinoma." (PMID 39505854, 2024). "The cBioPortal database was used to analyze the mutations of seven genes, which showed that E2F3, ETS2, HLF, HSF4, KLF4, MEIS2, and TCF7L1 were altered in 8, 8, 6, 6, 5, 9, and 6% of 524 colorectal adenocarcinoma patients separately." (PMID 34603375, 2021).
invasive breast carcinoma (2 papers, 2013 to 2014). A carcinoma that infiltrates the breast parenchyma. "Elevated expression of both Ets1 and Ets2 has been identified in invasive breast cancers and correlated with increased expression of p160 nuclear receptor coactivators." (PMID 23874775, 2013). "In addition, elevated expression of Ets1 and Ets2 identified in invasive breast cancers has been correlated with increased expression of the p160 nuclear receptor coactivators NCOA1 (SRC1) and NCOA3 (AIB/SRC3)." (PMID 23874775, 2013).
nasopharyngeal carcinoma (2 papers, 2019 to 2021). A carcinoma arising from the nasopharyngeal epithelium. "It is worth noting that similar enrichment of ETS motifs and the binding of ETS2 have been reported in Super-Enhancers identified in other contexts, such as skin SCC and nasopharyngeal cancer." (PMID 31306413, 2019).
Obesity (2 papers, 2023). Accumulation of substantial excess body fat. "Only 107 transcripts were DE and common to both the anxious and HFD-fed fish (padj < 0.05), with only 2 genes appearing also among the 231 anxiety–obesity DE genes in larvae (zgc:162730 and ets2 (v-ets avian erythroblastosis virus E26 oncogene homolog 2))." (PMID 37443828, 2023). "Furthermore, ETS2 has a diverse role in inflammatory processes, potential affecting the inflammatory state of obesity." (PMID 36986146, 2023).
ocular neoplasm (2 papers, 2008 to 2016). "Our findings suggest that the genes encoding ETS-1 and/or ETS-2 may play a role in the emergence and/or progression of ocular tumor." (PMID 18958307, 2008). "The exposure time allowing the readily detection of ETS-1 and ETS-2 by western blotting in the retina of wild-type CB6 mice gave highly saturated signals for ETS-1 protein extracted from eyes affected by ocular tumor." (PMID 18958307, 2008). "Our data suggest that ETS-1 and ETS-2 are involved in one or more signaling pathways activating the expression of a set of genes involved in ocular tumor progression and the probable acquisition of high metastatic potential by this tumor." (PMID 18958307, 2008). "We then investigated ETS-1 and ETS-2 gene expressions in a mouse model of pigmented ocular neoplasm." (PMID 18958307, 2008). "However, the levels of ETS-2 protein in eyes with ocular tumor could still be quantified and interpreted using this exposure time." (PMID 18958307, 2008). "The role of two members of the ETS (E26 avian leukemia oncogene) family of transcription factors, ETS-1 and ETS-2, has been investigated in many cancers but has not yet been studied in ocular tumors." (PMID 18958307, 2008). "Interestingly, in triplicate experiments using semi-quantitative PCR and western blotting to compare ocular tumors in Tyrp-1 mice with WT eyes at the same age, we found that ETS-2 mRNA levels were higher than ETS-1 mRNA levels, but ETS-1 protein levels were higher than ETS-2 protein levels." (PMID 18958307, 2008). "However, the results obtained did not determine whether ETS-1 or ETS-2 was increased exclusively in the retina and/or RPE per se and in the ocular tumor only or throughout the whole eye." (PMID 18958307, 2008).
ovarian carcinoma (2 papers, 2018 to 2023). A malignant neoplasm originating from the surface ovarian epithelium. "The binding of ETS-2 to LAIR-1 promoter leads to high expression of LAIR-1, may suppress the development of ovarian cancer." (PMID 29915163, 2018).
pancreatic adenocarcinoma (2 papers, 2021 to 2025). "Conversely, the expression levels of CCND1, DUSP2, ETS2, JUN, and RALGDS were decreased in lung and pancreatic adenocarcinomas with KRAS mutations." (PMID 33982211, 2021). "Among these transcription factors, ETS2 overexpression has been linked to the progression of pancreatic adenocarcinoma and associated with aggressive phenotypes, such as lymph node metastasis and vascular invasion." (PMID 41281751, 2025).
pituitary adenoma (2 papers, 2015 to 2025). "Finally, in the context of pituitary adenoma, ETS2 is involved in inhibition of PRL gene expression, and therefore, the decrease of ETS2 mRNA in PRL tumors is consistent with the observed hyperprolactinemia." (PMID 26322309, 2015).
primary sclerosing cholangitis (2 papers, 2024). "SNPs associated with primary sclerosing cholangitis (PSC), ankylosing spondylitis and Takayasu’s arteritis were also enriched in ETS2-target genes." (PMID 38839969, 2024). "In this work, colocalisation analyses nominate likely primary sclerosing cholangitis effector genes and biological mechanisms at five non-coding (UBASH3A, PRKD2, ETS2 and AP003774.1/CCDC88B) and one coding (SH2B3) primary sclerosing cholangitis loci." (PMID 39505854, 2024).
prostate adenocarcinoma (2 papers, 2017 to 2023). "Within this group of genes, Ets2 (V-ets erythroblastosis virus E26 oncogene homolog 2) and Skp2 (S-phase kinase-associated protein 2, p45) were identified as proto-oncogenes, and Krt14 (Keratin 14) is a structural protein that is widely used as a marker for prostate adenocarcinoma." (PMID 28874141, 2017).
rectum adenocarcinoma (2 papers, 2022 to 2023). An adenocarcinoma arising from the rectum. "Heterozygous amplifications of ETS2 and CDK6 in TGCT; CDK6 in GBM; E2F1 and ID1 in rectum adenocarcinoma (READ); and SP1, CDK4, and MDM2 in ACC were all greater than 70%." (PMID 35911954, 2022).